CCNB1 (cyclin B1)
Diseases named in the same sentence as CCNB1 in open-access papers (continued):
Sharing a sentence is not in itself a finding about the gene and the disease.
cancer (continued). "It has been reported that cyclin B1 overexpression could promote tumorigenesis and function as a putative oncogene in a variety of cancers." (PMID 39849382, 2025). "Additionally, CCNB1 expression correlated with MSI in cancers such as STAD, MESO, UCEC, ACC, SARC, KIRC, LIHC, and COAD." (PMID 38581717, 2024). "Numerous studies have demonstrated aberrant expression of CCNB1 in various types of cancer." (PMID 38581717, 2024). "Collectively, our results suggested that CCNB1 has the potential to serve as a valuable prognostic biomarker and may be a promising target for immunotherapy in various cancer types." (PMID 38581717, 2024). "Consequently, we assessed CCNB1 protein levels and discovered significant upregulation in nine cancer types." (PMID 38581717, 2024). "Among the top downregulated 50 genes, there were other cancer relevant genes such as cell cycle associated (CCNF1, CCNB1, ZWINT), cancer signaling (STK32B, IGF1, FLT1) and splicing associated (HNRNPM, HNRNPU, SRSF1) genes, which are active areas to investigate further." (PMID 38200580, 2024). "Several studies have indicated that CCNB1 may affect the pattern of immune infiltration in certain cancers." (PMID 38581717, 2024). "Notably, ACC and KIRP exhibited the area under the curve (AUC) values above 0.7, suggesting a substantial clinical significance of CCNB1 in differentiating between early and late disease stages in these cancers." (PMID 38581717, 2024). "Excitingly, in these cancers, CCNB1 protein expression aligned with the mRNA expression trends." (PMID 38581717, 2024). "We also assessed the relationship between the CCNB1 gene and immune checkpoint genes in pan-cancer." (PMID 38581717, 2024). "However, a statistically significant difference was observed between the pTa and pT2 cancer stage groups, with the pT2 group showing a higher fold increase in CCNB1 gene expression." (PMID 39795587, 2024). "Our findings demonstrated a significant increase in CCNB1 expression across 28 cancer types." (PMID 38581717, 2024). "In addition, we observed that an increase in CCNB1 expression correlates with a higher histological grade in ten types of cancer." (PMID 38581717, 2024). "Our study showed that DNA methylation of CCNB1 was downregulated in 14 cancer types." (PMID 38581717, 2024). "When Kolmogorov-Smirnov and Shapiro-Wilk tests were applied for CCNB1 in the pTa, pT1, and pT2 cancer stage groups, the pT1 group, which included six patient samples, showed a normal distribution (p > 0.05), whereas the pTa and pT2 groups did not follow a normal distribution (p < 0.05)." (PMID 39795587, 2024). "In cancer cells, CCNB1 levels are frequently dysregulated and significantly elevated." (PMID 39795587, 2024). "The dysregulation of CCNB1 results in uncontrolled cell growth and may contribute to the development of malignant tumors." (PMID 38581717, 2024). "Furthermore, CCNB1 expression was significantly correlated with M-stages in six cancer types, specifically COADREAD, KIRP, KIPAN, KIRC, LUSC, and ACC." (PMID 38581717, 2024). "Therefore, we examined the relationship between CCNB1 expression and immune infiltration in pan-cancer settings." (PMID 38581717, 2024). "It has been reported that cancer cells show increased expression levels of CCNB1." (PMID 39795587, 2024). "Therefore, our study aims to elucidate the role of CCNB1 across a spectrum of human cancers using bioinformatics methods." (PMID 38581717, 2024). "However, studies investigating the overexpression of CDC20 and CCNB1 have yielded varying results depending on cancer type." (PMID 39795587, 2024). "This discovery could potentially enhance the clinical significance of CCNB1 as a novel pathological staging marker for a range of cancer types." (PMID 38581717, 2024). "Analysis of the relationship between CCNB1 expression levels and cancer clinico-pathological stages indicated that abnormal CCNB1 expression could serve as a prognostic indicator in cancer patients." (PMID 38581717, 2024).
cancer (continued). "In our study, cyclin B1 phosphorylation differed between sensitive and resistant cancer cells." (PMID 38675591, 2024). "The expression of CCNB1 correlates with the development of cancer." (PMID 36984548, 2023). "In the current experimental study, we found that baicalin reduces the protein content in Cyclin B1 and p-cdc2 in all cancer cell lines, which might exhibit the molecular level effect via inducing the cell arrest at G2/M phase." (PMID 38094052, 2023). "Additionally, wogonin inhibits the cell cycle of cancer cell lines by inhibiting the expression of cyclin D1, cyclin B1, and CDK1, inducing apoptosis, improving the Bax/Bcl‐2 ratio, and increasing caspase‐3 cleavage." (PMID 37132286, 2023). "Moreover, WB and IF results also showed that CCNB1 was highly expressed in WT cell lines and cancer tissues, respectively." (PMID 37592341, 2023). "Downregulation of cyclin B1 can block the aggressive proliferation of cancer cells." (PMID 37759511, 2023). "Ccnb1 is significantly overexpressed in various cancer types including breast and prostate." (PMID 37398910, 2023). "Finally, we validated the differential expression level of CCNB1 in an external gene set, the pan-cancer, clinical samples, and cell lines." (PMID 37592341, 2023). "Thus, our results provide the basic evidence that HMGA1 and FOXM1 cooperatively accelerate cell cycle progression by up-regulating PLK1 and CCNB1 to promote cancer cell proliferation." (PMID 37240870, 2023). "CCNB1 was highly expressed, and promoter methylation was reduced in most cancers." (PMID 37758792, 2023). "The expression of CCNB1 in 33 different cancer types was extracted from The Cancer Genome Atlas (TCGA) and Genome Tissue Expression (GTEx), together with normal tissue transcriptome data, and the expression of CCNB1 in 33 types of cancer was analyzed." (PMID 36040381, 2022). "Structure-based virtual screening indicated that amentoflavone may exert its potential anti-cancer effects via targeting cyclin B1/CDK1 complex which was further validated by in vitro experiments." (PMID 35484963, 2022). "Our data show that chronic RT of PDAC cells results in upregulation of FDPS, cyclin D1, cyclin B1, and cancer stem cell markers in PDAC cells accompanied by altered cellular morphology, increased survival facilitated by G2/M arrest, and an increased side population." (PMID 34971971, 2022). "Therefore, CCNB1 dysregulation allows cancer cells to proliferate and differentiate, and the new cancer cells promote the expression of CCNB1 to increase further." (PMID 36247089, 2022). "The overexpression of CCNB1 has also been indicated as a poor outcome in some patients with cancer." (PMID 36601001, 2022). "This denoted that CCNB1 can distinguish the severity of this cancer." (PMID 35983531, 2022). "At present, the role of CCNB1 in a variety of cancers has been studied." (PMID 35456460, 2022). "CCNB1, as a core part of the cyclin family, was found in many cancers, especially in BC." (PMID 36040381, 2022). "Additionally, we also found significant decrease of phosphorylated form of cyclin B1 in ZK-CH-11d-treated cancer cells." (PMID 35335879, 2022). "Moreover, CCNB1 elicits T cell-dependent antibody responses not only in patients with cancer and premalignant disease, but also in healthy individuals." (PMID 34858418, 2021). "The recognized cancer genes CCNB1 and CCNB2 were also identified as WT-related genes." (PMID 33765954, 2021). "The following mechanism research revealed that hsa_circ_0001610 functioned as the competing endogenous RNA of miR-139-5p, thereby upregulating cyclin B1 expression, which is a vital pusher of radioresistance in several types of cancer by regulating the cell cycle." (PMID 34462422, 2021).
cancer (continued). "Shared genes by all cancers with an adverse prognosis (high positive global meta-z-scores), such as MAD2L1, CCNB1, NUF2 and UBE2C, were associated with gene ontology (GO) enrichment analysis terms related to proliferation, replication and mitosis, similar to adult tumors." (PMID 33670534, 2021). "CCNB1 is proven to be a prognosis-related biomarker in a variety of cancers, including BC." (PMID 34434217, 2021). "T-cells specific for multiple cyclin B1 specific CD4 T-cell epitopes could be expanded from both cancer patients and volunteer donors." (PMID 34526999, 2021). "Previous studies showed that ASPM, ACTC1, and CCNB1 are related to cancer prognosis." (PMID 34434217, 2021). "Among the 10 function MTIs, CCNB1 gave the highest connection degree, which was targeted by four miRNAs (hsa-miR-132-3p, hsa-miR-212-3p, hsa-miR-548b-3p, hsa-miR-410-3p) in experiment validation, suggesting its increasing correlation with human cancer." (PMID 33946043, 2021). "CCNB1 is a regulator of mitosis, and high levels of CCNB1 are found in many cancers including BC." (PMID 33466455, 2021). "The down-regulation of Cyclin B1, using specifically designed siRNAs, has shown to increase the apoptotic rate and to decrease proliferation and colony-forming ability of several cancer cells, denoting the importance of this cell-cycle regulator in the promotion of carcinogenesis." (PMID 34141616, 2021). "CMRP-induced increase in the levels of the phosphorylated form of histone variant, γ-H2AX, provided compelling and corroborative evidence of DNA damage, whilst reduction in cyclin B1 and Chk1 expression was indicative of the extract’s ability to influence the cell cycle of cancer cells." (PMID 33436696, 2021). "As Anthos inhibit molecules involved in EMT and downregulate various cyclins, including Cyclin B1, these could comprise a possible mechanism for Anthos to inhibit cancer metastasis." (PMID 34944868, 2021). "Defects of a mitotic checkpoint may bring about mistakes in the chromosome segregation, and the higher level of Cyclin B1 (CCNB1) is a marker of poor prognosis in many cancer types." (PMID 33632229, 2021). "Besides, CCNB1 decreases proliferation and S-phase cell proportion and increases apoptosis, senescence, and G0/G1-phase cell proportion in cancer." (PMID 34745136, 2021). "Cyclin B1 (CCNB1) is a regulatory protein involved in G2/M transition phase of the cell cycle and its encoding gene is highly correlated with glycolysis score and GAPDH expression across cancers." (PMID 32635458, 2020). "Consequently, downregulation of cyclin dependent kinase 1 (Cdk1-cyclin B1) signaling resulted in cell cycle arrest, and inhibition of cancer cell proliferation in HeLa, MCF-7, PC3, SKBr3-HER2 cancer cell lines." (PMID 32296681, 2020). "Cyclin B1 is a key cell cycle protein regulating the G2/M phase transition, contributing to the formation of PGCCs, highly correlating with the invasion and metastasis of various malignant tumors." (PMID 32154176, 2020). "Subsequently, immunohistochemical staining of xenograft tissues collected from nude mice demonstrated that knockdown of PRC1 could significantly inhibit the expression of cancer differentiation-related proteins (Cdc2, Cyclin B1, and ki67) (P < 0.05)." (PMID 33292244, 2020). "However, the overexpression of CCNB1 in cancer results in unchecked cell growth due to its binding to Cdks." (PMID 32219041, 2020). "CCNB1, CCNB2, and CCNA2 are the authorizing members of the cyclin family, critical for regulation of cellular growth, proliferation, and apoptosis; and consequently, associated with cancer development and progression." (PMID 32752229, 2020).
cancer (continued). "Furthermore, studies in cell lines suggests that cancer cells depend on a functional mitotic checkpoint and increased expression of CCNB1 and PTTG1 is therefore more likely a result of increased proliferation." (PMID 31801961, 2020). "CCNB1 was reported highly expressed in several different human cancers." (PMID 30651720, 2019). "Clinical studies have reported an overexpression of cyclin B1 in various human cancers." (PMID 31803360, 2019). "Some of them were reported to be cancer-related genes, such as CCNB1, EZH2, AXIN2, and FOXF2." (PMID 31321712, 2019). "In conclusion, the results of this study convincingly demonstrate that diosgenin treatment results in a decreased level of cyclin B1 and increased phosphorylation of Cdc25CSer216 and Chk1Ser345, leading to cell cycle blockade at the G2/M phase, disruption of the ∆Ψm, and apoptotic cancer cell death." (PMID 31881805, 2019). "Indeed, both upregulation of BUB1B and CCNB1 were found to be a marker for unfavourable prognosis across several cancer types." (PMID 31396397, 2019). "High levels of CCNB1 usually lead to cell immortalization, resulting in aneuploidy, which contributes to chromosomal instability and is related to the aggressive nature of certain cancers." (PMID 31828101, 2019). "The top 1 network in the spleens of A.SW mice was categorized as “Cell Cycle,” “Reproductive System Development and Function,” and “Cancer,” including down-regulated genes: cyclin family (Ccne1, Ccnb1, and Ccnb2) and cell division cycle family (Cdc20, Cdc25b, and Cdc25c)." (PMID 30941144, 2019). "Data suggest that cyclin B1 is involved in the development and progression of cancer." (PMID 29875662, 2018). "To explore whether circ-Ccnb1 could be developed as an agent for molecular therapy in cancer, we generated an expression construct expressing circ-Ccnb1 and a mock control." (PMID 29795334, 2018). "We found that a particular circular RNA circ-Ccnb1 was down-regulated in cancer samples." (PMID 29795334, 2018). "The possible mechanism behind this may be that the phosphorylation of GSK-3β causes much more stabilization of beta-catenin, which promotes the expression of cyclin-B1 and survivin, and thereby promotes the proliferation and survival of cancer cells." (PMID 30213025, 2018). "Silencing circ-Ccnb1 was also performed in a non-cancer cell line 293T." (PMID 29795334, 2018). "Conversely, the levels of Ccnb1 mRNA were higher in cancer samples relative to benign samples." (PMID 29795334, 2018). "Owing to its relationship with the chemotherapeutic resistance of several types of human cancers, cyclin B1 may also mediate the USP22‐induced MDR in HCC cells, which is valuable for future exploration." (PMID 28417539, 2017). "Moreover, inhibition of NCAPG2 suppressed cancer cell proliferation via leading to G2/M phase arrest through alterations of p27, p21, Cyclin B1 and Cdc2 expression." (PMID 27862966, 2017). "Of note, we found both CDK1 and CCNB1 in the list of switch genes shared by different cancer types." (PMID 28317894, 2017). "Overexpression of cyclin B1 has been reported in various human cancers, including breast, colorectal, lung, prostate, pancreatic, laryngeal, esophageal, gastric and hepatocellular cancers." (PMID 27903976, 2017).
cancer (continued). "Furthermore, the similar effects can be detected in different cancer cell lines, indicating B220 activates the Cdk1/cyclin B1 complex in cancer cells." (PMID 28963527, 2017). "The elevated level of CCNB1 indicates more aggressive cancer and poor prognosis." (PMID 27030811, 2015). "The increased expression of Cyclin D1 and Cyclin B1 can promote the cell transformation during the G1/S and G2/M phases, respectively, which enhances the cell proliferation level, and consequently leads to the occurrence of cancer." (PMID 25950458, 2015). "Cyclin B1, mapped to human chromosome 5q12, is known as a mitotic cyclin because of its key role in modulating G2/M phase progression of the cell cycle, and participates in cell growth, differentiation, apoptosis, and metastasis in various cancer types." (PMID 25962181, 2015). "Our predicted results corroborate with the established roles of AURKA and CCNB1 in cancers." (PMID 26317392, 2015). "Cyclin B1 facilitates the transition of the cells from G2 to M phase but becomes unregulated in cancer cells where overexpression of Cyclin B1 may contribute to uncontrolled cell proliferation." (PMID 27462423, 2015). "It is well documented that Cyclin B1 is unregulated in cancer cells where overexpression of Cyclin B1 may contribute to uncontrolled cell proliferation." (PMID 27462423, 2015). "14-3-3σ is vital at the G2/M checkpoint, as it sequesters the Cdc2/cyclin B1 complex; therefore, 14-3-3σ may be involved in the development of cancer." (PMID 25435977, 2015). "Cyclin B1 has been used as a prognostic indicator in those cancers." (PMID 25978027, 2015). "The expression levels of other mitotic factors including Cyclin B1 and Aurora A are comparable between basal-like and luminal cancer cells, suggesting that MELK may play a unique role during mitosis in BBC cells." (PMID 24844244, 2014). "Cyclin B1 plays an important role in progression of various cancers." (PMID 24690879, 2014). "In contrast to the hypophosphorylation of pRB, decrease in cyclin B1 and increase in cyclin D1 in ASH-WEX and TEG-treated cancer cells (undergoing growth arrest), normal cells showed increase in pRB phosphorylation and cyclin B1, and decrease in cyclin D1 (signifying their cell cycle progression)." (PMID 24130852, 2013). "Altered expression of cyclin B1 has been reported in numerous cancers, where it could contribute to chromosomal instability." (PMID 23835136, 2013). "S100A8/A9-dependent reduction in expression of cyclin B1 and hyperphosphorylation of p-Cdc2 (Thr14/Tyr15) shown in this study are consistent with Cdc2 inactivation and G2/M checkpoint arrest as commonly reported in carcinomas." (PMID 23874958, 2013). "Because the treatment with beta-carboline derivatives leads to accumulation of cancer cells at G2/M stage, wherein the degradation of cyclin B1 is prohibited, the cell cycle arrest induced by high concentration of DH166 may cause elevated cyclin B1." (PMID 23056340, 2012).